BCLAF1 (BCL2 associated transcription factor 1)
Diseases named in the same sentence as BCLAF1 in open-access papers (continued):
Sharing a sentence is not in itself a finding about the gene and the disease.
breast carcinoma (5 papers, 2019 to 2024). "A recent study reported that BCLAF1 upregulated PD-L1 expression under IR context in breast cancer, human fibrosarcoma, and prostate cancer cells." (PMID 38340178, 2024). "Heat shock protein 1B, NOB1 and CRIP1 were upregulated while BCLAF1 was downregulated in breast cancer after sublethal heat treatment." (PMID 35150481, 2022). "In the real data analyses we observed many pairs might have a gene in common, for instance, SPDEF in the breast cancer dataset and BCLAF1 and CDH3 in the lung cancer dataset." (PMID 32334509, 2020). "Knockdown of BCLAF1 in MCF7 breast cancer cells enhanced radiation-induced cell death suggesting that BCLAF1 could promote resistance to radiation-induced DNA damage." (PMID 30678233, 2019). "The deletion also encompassed MTFR2 and BCLAF1 genes, the latter one was recently related to the regulation of the PDL1 pathway in breast cancer." (PMID 39239354, 2024). "Based on the data of The Human Protein Atlas, BCLAF1 and DDX5 had an unfavorable prognostic factor among breast cancer patients, although only BCLAF1 reached statistical significance." (PMID 30678233, 2019). "With mass spectrometry and immunoprecipitation analysis, three potential TRIB3-interacting proteins were identified and two of them, BCLAF1 and DDX5, served as poor prognostic factors in breast cancer patients at the protein level." (PMID 30678233, 2019). "With the web resource of UALCAN, the mRNA expression of BNIP1 (p = 0.048) and BCLAF1 (p = 0.00014) displayed a significantly negative correlation with breast cancer patients’ overall survival." (PMID 30678233, 2019).
leukemia (5 papers, 2015 to 2025). A malignant (clonal) hematologic disorder, involving hematopoietic stem cells and characterized by the presence of primitive or atypical myeloid or lymphoid cells in the bone marrow and the blood. "In summary, based on the results obtained in this study, we can claim that the regulators ZBTB7A and PU1 beside to BCLAF1 and NRSF play a significant role in cancer, and especially in leukemia." (PMID 33828122, 2021).
gastric cancer (3 papers, 2021 to 2025). A primary or metastatic malignant neoplasm involving the stomach. "The upregulation of BCLAF1 Ser290 phosphorylation (pBCLAF1 (Ser290)) in tumor was confirmed by tissue microarray studies and further indicated in association with poor prognosis of gastric cancer patients." (PMID 34372878, 2021). "BCLAF1 is a key regulator of TNF-α-induced apoptosis, and the phosphorylation of BCLAF1 at Ser290 is involved in the regulation of the DNA damage response, eliminating the phosphorylation of BCLAF1 at Ser290 and suppressing gastric cancer (GC) cell proliferation." (PMID 40732187, 2025). "Eliminating the phosphorylation of BCLAF1 at Ser290 suppressed gastric cancer (GC) cell proliferation." (PMID 34372878, 2021).
prostate carcinoma (3 papers, 2019 to 2024). A carcinoma that arises from epithelial cells of the prostate gland. "While this antibody was previously validated with LINE-1 overexpression and knockdown experiments, our findings show that in LNCaP prostate cancer cells, the chA1-L1 antibody also recognizes BCLAF1." (PMID 31890047, 2019).
viral infection (3 papers, 2019 to 2025). "BCLAF1 is also involved in type I interferon signaling and regulates antiviral gene expression upon virus infection." (PMID 35579274, 2022). "Our studies establish the importance of Bclaf1 in IFNα-induced antiviral immunity and in the control of viral infections." (PMID 30682178, 2019). "Thus, to determine the role of Bclaf1 in viral infection, we focused on the differential properties between WT and ΔUS3 PRV infected cells." (PMID 30682178, 2019). "Subsequent studies have revealed the extensive roles of BCLAF1 in various processes, ranging from the DNA damage response (DDR), pre-mRNA splicing, and T cell activation to lung development, muscle cell proliferation/differentiation, autophagy, ischemia–reperfusion injury, and viral infection." (PMID 41472165, 2025).
atherosclerosis (2 papers, 2022 to 2023). A disease characterized by the build-up of fatty material and calcium deposition in the arterial wall resulting in partial or complete occlusion of the arterial lumen. "KLF4 and BCLAF1 initiate SMC phenotypic switch in atherosclerosis by inducing SMC lipid transdifferentiation, whereas KLF11 has been shown to inhibit arterial thrombosis." (PMID 36188622, 2022). "Our study also identified specific atherosclerosis-related transcription factors KLF4, KLF11 and BCLAF1 upstream from FURIN, PCSK6 or PCSK7." (PMID 36188622, 2022).
glioma (2 papers, 2018 to 2023). A benign or malignant brain and spinal cord tumor that arises from glial cells (astrocytes, oligodendrocytes, ependymal cells). "BCLAF1 acts in a positive feedback loop enhancing PDGFRa and EGFR signaling in high-grade glioma." (PMID 37579831, 2023).
HCMV infection (2 papers, 2021 to 2025). "HCMV infection stimulates degradation restriction factors including Daxx, PML, and BclAF1 (10, –, 12, 38)." (PMID 39655950, 2025). "Concerning its role during HCMV infection, Lee and colleagues depleted BclAF1 by transfection of siRNAs and observed increased IE1 protein expression without affecting pp71 levels suggesting that BclAF1 may repress viral IE gene expression." (PMID 33530304, 2021).
ovarian carcinoma (2 papers, 2016 to 2022). A malignant neoplasm originating from the surface ovarian epithelium. "We also identified several novel hub genes that were previously unreported in ovarian cancer, such as BCL2-associated transcription factor 1 (BCLAF1), ADP-ribosylation factor-like 8B (ARL8B), and SEC31 homolog A (S. cerevisiae) (SEC31A)." (PMID 26972162, 2016). "In this study, we also showed that parent genes such as BCLAF1, FBLN1, ARHGAP23, STON2, UBQLN4, and ATP2B1 were significantly positively correlated with the survival rate of patients with ovarian cancer." (PMID 35978436, 2022). "We found that the expression of six genes (BCLAF1, FBLN1, ARHGAP23, STON2, UBQLN4, and ATP2B1) had a significant positive correlation with the survival rate of patients with ovarian cancer." (PMID 35978436, 2022).
adenoma (1 paper, 2024). A neoplasm arising from the epithelium.
cervical cancer (1 paper, 2024). A primary or metastatic malignant neoplasm involving the cervix. "One related study revealed that BCLAF1 affects post-translational modifications to stabilize PD-L1 protein in the context of IR in breast, prostate, and cervical cancer cell lines." (PMID 38340178, 2024). "A previous study showed that BCLAF1 upregulates PD-L1 protein levels in breast, prostate, and cervical cancer cell lines in the context of ionizing radiation (IR), and this molecular event was validated by IHC in human esophageal squamous carcinoma tissue." (PMID 38340178, 2024).
chronic heart failure (1 paper, 2023). "To further validate our phosphoproteomic findings, we assessed protein level of Bclaf1 Ser658 with Western blotting from other post-infarction chronic heart failure/SO rats." (PMID 37405054, 2023). "In this study, we intersected DPPs with Thanatos Apoptosis Database and identified Bclaf1 Ser658 as a potential critical phosphorylated protein of apoptosis in post-infarction chronic heart failure." (PMID 37405054, 2023). "Expression level of Bclaf1 Ser658 was increased post-infarction chronic heart failure rats, which is consistent with the previous phosphoproteomic analysis." (PMID 37405054, 2023). "In this study, Bclaf1 was phosphorylated at Ser658 in post-infarction chronic heart failure." (PMID 37405054, 2023).
colon adenocarcinoma (1 paper, 2021).
COVID-19 (1 paper, 2023). A disease caused by infection with severe acute respiratory syndrome coronavirus 2. "However, these apoptotic gene signatures were characterized by distinct DEGs expressed in the COVID-19(+) TV (BCLAF1, BCL2L1) and COVID-19(-) PU control groups (BAD, ACIN1, HIF1A)." (PMID 37026002, 2023).
epilepsy (1 paper, 2021). A brain disorder characterized by episodes of abnormally increased neuronal discharge resulting in transient episodes of sensory or motor neurological dysfunction, or psychic dysfunction. "Consistent with their studies, we also observed downregulation of anti-apoptotic genes (CDKN1A, YWHAB, etc.)and upregulation of pro-apoptotic genes (BCLAF1, etc.)in human epilepsy samples." (PMID 34867172, 2021).
heart failure (1 paper, 2023). Inability of the heart to pump blood at an adequate rate to meet tissue metabolic requirements. "Bclaf1 Ser658 might play a critical role in apoptosis in heart failure." (PMID 37405054, 2023).
hereditary cancer (1 paper, 2021). Malignant neoplasms occurring in families at a rate greater than that expected by chance and caused by germline mutations in a specific gene. "In addition, nonsense variants in apoptosis-related genes TP53AIP1, BCLAF1, and PIK3C2G were identified in our cohort; highlighting the potential relevance of genes involved in apoptotic processes to hereditary cancer." (PMID 33782397, 2021).
herpesvirus infections (1 paper, 2019). "Bclaf1 was degraded by both genera of alphaherpeviruses and was also inhibited by members of beta- and gammaherpesviruses, indicating that the disruption of Bclaf1 might be a general mechanism for all herpesvirus infections." (PMID 30682178, 2019).
Hypertension (1 paper, 2019). The presence of chronic increased pressure in the systemic arterial system. "Bclaf1 also enhances proliferation of endothelial cells, in the context of delivery of microRNA miR-143-3p via platelet-derived microparticles in a hypertension model." (PMID 30367150, 2019).
latent infection (1 paper, 2022). "In addition, US3 could interfere type I interferon reaction by degrading Bcl-2 associated transcription factor 1 (Bclaf1), and inhibit with MHC I-mediated antigen presentation, which can promote the establishment of latent infection in PRV to some extent." (PMID 36298468, 2022).
osteoarthritis (1 paper, 2025). A noninflammatory degenerative joint disease occurring chiefly in older persons, characterized by degeneration of the articular cartilage, hypertrophy of bone at the margins and changes in the synovial membrane. "By investigating the expression patterns and functional impacts of BCLAF1 in OA models, we demonstrated its potential as a biomarker and therapeutic target in the treatment of osteoarthritis." (PMID 39990659, 2025). "In the present study, we explored the role of BCLAF1 in osteoarthritis, hypothesizing that BCLAF1 contributes to OA pathogenesis through its involvement in chondrocyte apoptosis and inflammatory responses." (PMID 39990659, 2025).
Parkinson (1 paper, 2022). "However in dopamin neurons of patients with Parkinson, it is indicated that BCLAF1 is downregulated which is associated with programmed cell death and mitochondrial function." (PMID 36418457, 2022).
seminoma (1 paper, 2022). A radiosensitive malignant germ cell tumor found in the testis (especially undescended), and extragonadal sites (anterior mediastinum and pineal gland). "Interestingly, our analysis found that the long isoform of BCLAF1 with exon 11 included was upregulated in seminoma and validated in TCam2 cells." (PMID 36713456, 2022).
tongue cancer (1 paper, 2026). A malignant neoplasm affecting the tongue. "CDC27 together with BCLAF1 and AQP7 show substantial changes in HPV-related tongue cancers, especially CDC27 deletions that correlate with tumour recurrence." (PMID 41487403, 2026).
triple-negative breast carcinoma (1 paper, 2020). An invasive breast carcinoma which is negative for expression of estrogen receptor (ER), progesterone receptor (PR), and human epidermal growth factor receptor 2 (HER2). "Our previous study revealed that TRIB3 can interact with DDX5/BNIP/BCLAF1 in radioresistant MDA-MB-231 cells; thus, it is involved in the self-renewal and radioresistance of triple-negative breast cancer cells by regulating Notch1 activation." (PMID 33334065, 2020).
cancer (35 papers, 2014 to 2026). A tumor composed of atypical neoplastic, often pleomorphic cells that invade other tissues. "BCLAF1 showed a non-significant trend for enrichment in TMB-high non-responders (OR = 0.67 [0.19–2.33], p > 0.05) which emphasizes the need for additional pan-cancer data to determine if the BCLAF1 association generalizes widely." (PMID 35803911, 2022). "Among the genes affected by the most common unique variants, BCLAF1 is the best-studied in the cancer setting as an associated transcription factor for Bcl2." (PMID 35008243, 2021). "Notably, Bcl-2-associated transcription factor 1 (BCLAF1), a death-promoting transcriptional repressor highly expressed in a variety types of cancer, is shown to be phosphorylated at multiple positions." (PMID 34372878, 2021). "Moreover, we show that cancer associated mutations within THRAP3 result in deregulated processing of THRAP3/BCLAF1-regulated transcripts and consequently defective DNA repair." (PMID 29112714, 2017). "The cancer research field has extensively studied BCLAF1 as a transcription factor that binds to Bcl2 among the genes that frequently undergo mutations." (PMID 41487403, 2026). "The cell viability of cancer cells transfected with WT BCLAF1 was significantly higher than the cells with empty vector transfection." (PMID 34372878, 2021). "For example, studies have found that the downregulated expression of circRNA circ-Ccnb1 in breast cancer can interact with Bclaf1 in cancer cells through H2AX, resulting in the inhibition of uncontrolled division and growth of cancer cells." (PMID 33884267, 2021). "BCLAF1 was originally described as a protein interacting with anti-apoptotic members of the BCL2 family, and more recently, it has been linked to cancer cell proliferation, invasion, and drug resistance." (PMID 34356831, 2021). "Two key proteins, H2AX and Bclaf1, which function in DNA repair and cell mitosis, play roles in cancer development." (PMID 32194627, 2020). "Compared with para-carcinoma tissues, the relative expression level of BCLAF1 was significantly increased about 1.82 times of BC samples (P=0.002)." (PMID 33188158, 2020). "A high incidence of somatic mutations of BCLAF1, U2AF65, U2AF35, SRSF2, SF3A1, SF3B1, and PRPF40B at the BRCA1/BCLAF1 mRNA splicing complex was reported in various cancer types." (PMID 32010626, 2019). "Consistent with this view, SRSF10 controls the alternative splicing of exon 5a in BCLAF1 in a variety of cancer cell lines." (PMID 27851963, 2016). "We also identified a number of ‘cancer genes'18 as significantly mutated in PDA, including BCLAF1 (5% of cases), IRF6 (4% of cases), FLG (10% of cases), AXIN1 (5% of cases), GLI3 (6% of cases) and PIK3CA (4% of cases)." (PMID 25855536, 2015). "Indeed, BCLAF1 has been reported to regulate several apoptotic genes and promote apoptosis in various cancers." (PMID 41136394, 2025). "Interestingly, this finding is consistent with BCLAF1’s well-known role as a death-promoting TF with significantly upregulated gene expression in many cancer types." (PMID 37695793, 2023). "Moreover, several cancer-promoting factors, such as Bclaf1, PRMT1, and angiotensin II, have been reported in the transcriptional regulation of HIF-1α." (PMID 33716751, 2021).